MAPT (microtubule associated protein tau)
Diseases named in the same sentence as MAPT in open-access papers (continued):
Sharing a sentence is not in itself a finding about the gene and the disease.
cancer (continued). "There are relatively fewer studies discussing the role of MAPT in cancer." (PMID 16608523, 2006). "Recent reports revealed that MAPT may related to the prognosis of certain cancers." (PMID 35252219, 2021). "Remarkably, tumors in those tissues lie among the group of cancers with higher Tau/MAPT expression, suggesting that this gene could have other functions beyond chemoresistance and could be associated with intrinsic properties of the cells in the different organs." (PMID 31551755, 2019). "As an effective pharmacological compound for cancer, LA induces apoptosis in different cancers via multiple pathways, including P13-Akt-mTOR, VEGFR2, c-Met, PLCγ1, MAPT, JNK/p38, and ERK1/2, along with a combination of regulatory targets." (PMID 35677438, 2022). "The analysis of MAPT gene transcription and TAU protein expression in healthy and neoplastic tissues supports a role of TAU in cancer." (PMID 33207722, 2020). "Besides common nodes such as CYPs, APEX1, MAPT, which reflect the same function for cancer, cardiovascular and neurodegenerative as other flavonoid subclasses flavones contains other nodes such as ALDH1A1 in module 5, which reflect potential associations with cancer invasion." (PMID 30158870, 2018). "We did this by in silico analyses of MAPT and CDA expression levels in several cohorts of cancer cell lines and tissues." (PMID 28947735, 2017). "The number of genes displaying a positive or negative correlation with MAPT expression was highly variable across cancers." (PMID 37730697, 2023). "MAPT was absent in normal prostate epithelial cells but detectable in 1004 (8.2%) of 12,313 interpretable cancers." (PMID 30823906, 2019). "Our data demonstrate strikingly higher MAPT expression levels in ERG positive than in ERG negative cancers." (PMID 30823906, 2019). "These associations held also true in the subsets of ERG negative and ERG positive cancers, although not all p values remained significant probably due to the overall small numbers of MAPT positive cancers." (PMID 30823906, 2019). "Finally, relevant subtypes have been described for some cancer types (e.g. BRCA and COAD) and alterations of MAPT expression could be attributed partially to the presence or prevalence of such subtypes, but this was not directly addressed in this study." (PMID 37730697, 2023). "All cancers showed distinct areas with and without MAPT staining." (PMID 30823906, 2019). "High MAPT expression levels were also associated with a higher risk for biochemical recurrence in all cancers and in the subsets of ERG positive and ERG negative cancers (p < 0.0001 each)." (PMID 30823906, 2019). "Also, after systemically analysis of targets for different flavonoids subclasses, it can be found that targets such as MAPT, APEX1, and ALDH1A1, which were closely related with nervous system and cancer, were significantly enriched in almost all flavonoid subclasses." (PMID 30158870, 2018). "MAPT staining was seen in 15.2 and 16% of cancers with TMPRSS2:ERG fusion detected by immunohistochemistry and fluorescence in-situ hybridization, but in only 3.5 and 3.9% of cancers without ERG staining or ERG rearrangements." (PMID 30823906, 2019).
tumor (42 papers, 2013 to 2026). "Dysregulation or mutation of MAPT can result in cytoskeletal reorganization, thereby promoting enhanced migration and invasiveness of tumor cells." (PMID 39600313, 2024). "This was consistent with the findings that high TUBB3 expression and microtubule-associated protein tau (MAPT) inversely correlated with the sensitivity to paclitaxel in cells isolated from fresh tumor tissue." (PMID 32751679, 2020). "MAPT expression levels were significantly associated with advanced tumor stage, high Gleason grade, positive nodal stage, and positive resection margin (p ≤ 0.0011 each)." (PMID 30823906, 2019). "MAPT overexpression was associated with to unfavorable tumor phenotype and early biochemical recurrence in this study (p < 0.0001 each)." (PMID 30823906, 2019). "Finally, we identified strong downregulation of MAPT (encoding Tau, a microtubule associated protein) expression as a reliable predictive marker for tumor cell X55 sensitivity." (PMID 35925417, 2022). "The significance of MAPT in tumor progression is primarily demonstrated through its influence on cytoskeletal regulation." (PMID 39600313, 2024). "In the LIHC dataset, we found a comparable group of normal-adjacent samples, which demonstrated the upregulation of EEF1A2, NUPR1, and MAPT proteins in the tumor group." (PMID 37628602, 2023). "It should be noted that the down-regulation of MAPT expression is a reliable predictive marker of drug sensitivity in tumor cells." (PMID 36671437, 2022). "A decrease in MAPT expression therefore appears to be a predictive marker of tumor cell sensitivity to X55." (PMID 35925417, 2022). "In several tumor types, MAPT has been suggested to represent a potential predictive marker in patients treated with taxanes." (PMID 30823906, 2019). "Transcriptomic profile analysis showed that two genes (L1CAM and FBN1) were upregulated and that four genes (AUST2, MAPT, AGT and USH1C) and two microRNAs (hsa-mir-100 and hsa-mir-378) were downregulated, all of which were associated with tumor malignancy." (PMID 29215599, 2017). "In particular, interferons and inflammation-related genes could suggest a link between MAPT expression and inhibition of anti-tumor immune response, with possible therapeutic implications given the fast-paced clinical implementation of the immunotherapy." (PMID 37730697, 2023). "We found a strong decrease in MAPT levels in response to X55, by more than 50%, in all X55-sensitive CDA-deficient tumor cells tested, whereas X55 treatment did not affect MAPT levels in X55-resistant CDA-deficient tumor cells." (PMID 35925417, 2022). "TIMER analysis also indicated a correlation between MAPT expression and immune infiltration, suggesting that MAPT might have a function in tumor immunity." (PMID 34406386, 2021). "SYN2 and MAPT were overexpressed in all tumor samples compared to normal samples." (PMID 35252219, 2021). "Another study found that MAPT knockdown enhanced cell growth and invasion and suggested that tau may be a tumour-suppressive protein in clear cell renal cell carcinoma." (PMID 32728795, 2020). "However, our findings suggest the potential tumor suppression function of MAPT and AUTS2 in the progression of ccRCC." (PMID 29215599, 2017). "Not only the elevated level of MAPT transcription rates in tumor tissue, but also a disproportion between 3RD and 4RD MAPT isoforms might have an impact on pathological changes." (PMID 26824039, 2016). "A prognostic index for tumor samples could be calculated by the formula: IRGPI = (HTN3 expression * 0.096) + (CTSG expression * −0.152) + (MAPT expression * 0.122) + (CCL28 expression * −0.094) + (PTX3 expression * 0.138) + (SEMA3G expression * −0.140) + (USP2 expression * 0.107)." (PMID 36845378, 2023).
tumor (continued). "The mutations in this tumor included 3 predicted high impact mutations in MTOR a regulator of stress response, OGT a glycosyltransferase that modifies a broad range of targets including H2B, AKT1, EZH2, PFKL, KMT2E/MLL5, MAPT/TAU and HCFC1, and FAM129B a negative regulator of apoptosis." (PMID 28415633, 2017). "Although MAPT is predominantly expressed in neurons, its overexpression in HCC has been shown to inhibit autophagosome-lysosome fusion, thereby promoting tumor progression." (PMID 41614774, 2025). "Patients whose tumour had high expression of MAP1LC3A, SNCA, and MAPT and low expression of CDK1, AP1S1, CASP3, TMPRSS6, and GSK3B inferred better overall survival than all other patients." (PMID 38642129, 2024). "We assessed the expression of PINK1.AS, OIP5.AS1, HID.AS1, and MAPT.AS1 in tumor pairs using qRT-PCR, which revealed a marked increase in the expression of these chrlncRNAs in tumor tissues compared to adjacent tissues." (PMID 38326441, 2024). "MAPT is overexpressed in a variety of tumor cells, including HCC, which promotes tumor cell proliferation and metastasis and induces tumor cell resistance to paclitaxel." (PMID 37322434, 2023). "However, there was no statistical difference in the mRNA expression of FABP4 and MAPT between tumor tissues and normal tissues of COAD patients, but the downward trend of FABP4 and MAPT expression in tumor tissues could still be seen, which may need to be verified by more clinical samples." (PMID 36203457, 2022). "We found that the expression levels of two upregulated genes (L1CAM and FBN1) were also increased along with tumor grade and that the expression levels of four downregulated genes (AUTS2, MAPT, AGT and USH1C) were decreased along with tumor grade." (PMID 29215599, 2017). "With regards to the clinical analysis of ccRCC samples from microarrays of GSE66272 and GSE73731, the upregulation of L1CAM and FBN1 and downregulation of AUTS2, MAPT, AGT and USH1C were observed along with an increase in tumor grade." (PMID 29215599, 2017). "For example, FOXA1, MLPH, NAT1, MAPT and BAG1 are expressed in luminal tumours according to published mRNA profiles and also co-clustered in our data, with higher expression levels in most ERPR tumours." (PMID 26725330, 2016). "We first compared the expression differences of MAPT, WDR62, PLK1, CDCA8 and TOP2A in normal hepatocyte tissues and HCC tissues by TCGA database, and the results showed that the expression levels of MAPT, WDR62, PLK1, CDCA8 and TOP2A were significantly higher in tumour cells than in normal tissues." (PMID 39072983, 2024). "In addition, 33 survival-related genes were observed to be elevated in tumor tissues, whereas 4 genes (RBP4, ABCB1, SCNA, and MAPT) showed increased expression in normal tissues." (PMID 35873484, 2022). "Again, a significant decrease in MAPT levels was observed in the two X55-sensitive CDA-proficient tumor cells, but not in X55-resistant CDA-proficient tumor cells." (PMID 35925417, 2022). "mRNA levels of SEPT9 and HIST1H2BH in tumor tissues were significantly higher than those in adjacent normal tissues, while that of MAPT was lower (p < 0.05)." (PMID 34854250, 2022). "Notably, a weak but significant correlation between MAST4 and MAPT gene expression (r = 0.37, p = 0.0001) was depicted in tumor samples but not in normal tissues." (PMID 37835564, 2023). "Of interest, six proteins (FOXA1, ERBB2, MAPT, NAT1, PHGDH, KRT5) and one protein (PHGDH) overlapped between PAM50 and the differentially expressed proteins between basal-like and luminal-like subtypes in microdissected tumor epithelium and stroma, respectively." (PMID 37349288, 2023). "Thus, MAPT levels decrease by more than 50% in all X55-sensitive tumor cell lines, regardless of their CDA expression status, but not in X55-resistant tumor or nonmalignant cell lines." (PMID 35925417, 2022).
neurological diseases (27 papers, 2010 to 2025). "MAPT, encoding microtubule-associated protein tau, plays an important role in nervous system disease." (PMID 36110953, 2022). "HDAC6 is reported to interact with microtubule-associated protein tau and is likely to be responsible for acetylation–phosphorylation switch of tau to affect neurological diseases progression." (PMID 31652644, 2019). "Among these pathological proteins, the microtubule-associated protein tau forms intraneuronal filaments in a spectrum of neurological disorders." (PMID 24278740, 2012). "The presence of at least one putative TDP-43 binding site in the human MAPT 3’UTR suggests that this may be contributing to the neurological disorder risk." (PMID 39149473, 2024). "A focused examination of six AD-related genes – APOE, APP, BIN1, CLU, MAPT and PSEN1 – and SMARCA5, which has been linked to neurological disorders, revealed different expression patterns across cell types and AD." (PMID 41255979, 2025). "For example, the human MAPT/TAU gene produces transcripts containing short or long 3’ UTRs, and a 3’ single-nucleotide polymorphism, (SNP) is associated with both 3’ UTR length and risks for 8 neurological disorders, including Alzheimer’s and Parkinson’s diseases." (PMID 39149473, 2024). "In our study in chronic HIV infection, we identified a strong association between plasma levels of SIRT2 with other prominent biomarkers of neurological disorders, such as BDNF, MAPT, and SNCA (32, –, 34)." (PMID 36719240, 2023).
movement disorder (7 papers, 2009 to 2025). Neurological conditions resulting in abnormal voluntary or involuntary movement, which may impact the speed, fluency, quality and ease of movement. "Intron 10 (IVS10) and other MAPT mutations that increase 4R tau production often lead to movement disorder phenotypes similar to sporadic PSP or CBD." (PMID 37317972, 2023). "In our highly selected population (cases of MAPT, PGRN and C9orf72 causing FTLD and a movement disorder), the most common gene involved was MAPT with a prevalence of 44% followed by PGRN (32%) and C9orf72 (24%)." (PMID 27100392, 2016). "Mutations in MAPT are the cause of autosomal dominant forms of frontotemporal lobar degeneration (FTLD) that present most commonly with behavioral variant FTD, but sometimes with movement disorders." (PMID 37317972, 2023).
psychiatric disorder (7 papers, 2021 to 2026). A disorder characterized by behavioral and/or psychological abnormalities, often accompanied by physical symptoms. "These include five genes encoding proteins that aggregate in neurodegenerative and/or mental illness: CRMP1 (also called DPYSL1), DISC1, MAPT (encoding the Tau protein), PRKN (also called PARK2, encoding Parkin), and SOD1." (PMID 42194081, 2026).
brain disease (5 papers, 2016 to 2021). "For the promise of precision medicine for brain disorders to be fulfilled, it is necessary to integrate known genetic causes of disease, i.e., MAPT mutations, with an understanding of the dysregulated molecular pathways that constitute potential therapeutic targets." (PMID 33255694, 2020). "The predicted affinity of compounds 1a–f at microtubule-associated protein tau, PTGS1/PTGS 2 and their predicted brain disorders applicability." (PMID 34299440, 2021). "Furthermore, as p-MAPT neuropathology can be associated with diverse brain diseases, we eliminated cases with brain pathologies that might affect the pattern of p-MAPT neuropathology or that might affect our immunohistochemical detection of p-MAPT neuropathology." (PMID 27793193, 2016). "This included brain disease traits with expression in the nervous system (antisense to APP and two antisense lncRNAs to MAPT) as well as immune-related diseases and enrichment in immune cells (antisense to LRRK2 and C9orf72)." (PMID 30610612, 2019).
infection (2 papers, 2022 to 2024). The state of being infected such as from the introduction of a foreign agent such as serum, vaccine, antigenic substance or organism. "Based on our findings, we hypothesize that mutations in APP, MAPT, and PSEN1 genes yield a compounding effect with age, triggering biological changes which initiate an inflammatory response that mimics the effects of LPS stimulation, despite the absence of infection." (PMID 38909241, 2024).
central nervous system disorder (1 paper, 2022). A disease involving the central nervous system. "Thus, providing further evidence and reaffirming the involvement of MAPT in central nervous system disorders." (PMID 35931958, 2022).
digestive system tumors (1 paper, 2021). "Of these PPLS, only two proteins were found to be dysregulated in all four digestive tumors, including syn2 and MAPT." (PMID 35252219, 2021). "The expression analysis of LLPS regulatory factors showed that a variety of LLPS regulatory factors were significantly dysregulated in digestive system tumors, such as SYN2 and MAPT." (PMID 35252219, 2021).
MAPT also shares sentences with these, for which no sentence is quoted: argyrophilic grain disease (15 papers); familial Alzheimer disease (8); Richardson syndrome (4); Type 2 diabetes (4); Ataxia (3); genetic disorder (3); hereditary ataxia (3); paraganglioma (3); pheochromocytoma (3); rheumatoid arthritis (3); atherosclerosis (2); autosomal dominant disease (2); cardiomyopathy (2); cognitive disorder (2); Creutzfeldt-Jakob disease (2); Crohn disease (2); Hallucinations (2); Hodgkins lymphoma (2); Hypertension (2); neurodevelopmental disorder (2); Niemann-Pick disease type C (2); osteoporosis (2); sarcoma (2); Tremor (2); abdominal aortic aneurysm (1); adenocarcinoma (1); afibrinogenemia (1); alcohol abuse (1); Arrhythmia (1); Auditory hallucination (1).
A further 72 diseases each share a sentence with MAPT in 1 paper.